MYC (MYC proto-oncogene, bHLH transcription factor)
Diseases named in the same sentence as MYC in open-access papers (continued):
Sharing a sentence is not in itself a finding about the gene and the disease.
colorectal cancer (continued). "The study found that metabolic reprogramming in colorectal cancer is primarily driven by aberrant MYC expression, occurring as early as the adenoma stage." (PMID 40419963, 2025). "We found that MYC and WNT associated signature scores of the reverted colorectal cancer cells (KD) were lower than those of the colorectal cancer cells (C)." (PMID 39661721, 2025). "MYC is an oncogene and encourages progression to neoplasia in many malignancies including colorectal cancer." (PMID 38609520, 2024). "Certainly, given the functional specificity of lncRNAs in different tumors, simultaneous targeting of specific lncRNAs with MYC in colorectal cancer is expected to improve the specificity of therapeutic effects." (PMID 39075086, 2024). "Collectively, our results shed new light on the ubiquitination of c-MYC, presenting a promising avenue for the development of innovative therapeutic strategies aimed at overcoming chemoresistance in colorectal cancer." (PMID 38163859, 2024). "We observed significant differences in the expression levels of STAT3 and MYC in colorectal cancer tissues." (PMID 39830506, 2024). "Concomitant sequencing of eccDNAs and RNA from the same cell uncovers the absence of correlation between eccDNA copy number and gene expression levels, except for a few oncogenes, including MYC, contained within a large eccDNA in colorectal cancer cells." (PMID 38409079, 2024). "According to the FDR value obtained, the main mechanisms involving the interrogated genes were those responsible for nasopharyngeal carcinoma and colorectal cancer mediated by MYC overexpression." (PMID 39125744, 2024). "The PVT1 gene functions as a newly discovered oncogenic enhancer of MYC, and its activity is regulated by epigenetic mechanisms involving abnormal methylation in colorectal cancer." (PMID 39830506, 2024). "In colorectal cancer, CREB1 activates the transcription of CCAT1 (colon cancer associated transcript 1), which upregulates MYC, a potent oncogene." (PMID 39883338, 2024). "Arginine 34 of CREPT was identified as a critical residue for the interaction with MYC, and its mutation lost the ability of CREPT to promote MYC-driven colony formation and tumor growth in colorectal cancer models." (PMID 39615685, 2024). "Our study also revealed a strong correlation between CREPT and MYC expression in various human cancers, particularly in colorectal cancer, where their interaction appears to play a significant role in tumorigenesis." (PMID 39615685, 2024). "Investigation of MYC and NCAPG2 mutations promises to refine colorectal cancer subtyping, thereby contributing to development of more precise treatment modalities." (PMID 38637125, 2024). "To visualize ecDNA hubs during mitosis using live-cell imaging, we used the colorectal cancer COLO 320DM cell line with a Tet-operator (TetO) array inserted into MYC ecDNAs and fluorescently labelled ecDNA molecules using TetR-mNeonGreen." (PMID 39506152, 2024). "Our findings are in line with a recent study of age-specific proteomic features in colorectal cancer, which similarly showed enrichment of MYC targets in colorectal patients above 50 years of age55." (PMID 38762630, 2024). "The suppressive role of miRNA-487b was also indicated in colorectal cancer via targeting MYC, SUZ12 and KRAS." (PMID 37108073, 2023). "In human colorectal cancer, the lncRNA CCAT1-L was implicated in chromatin looping at the MYC locus." (PMID 37444543, 2023). "We also demonstrated that NEK8-induced colorectal cancer proliferation relied on the serine 405 phosphorylation of c-MYC." (PMID 37596667, 2023). "To further confirm the correlation between NEK8 and c-MYC, we analyzed the expression level of NEK8 and c-MYC in 69 cases of colorectal cancer tissues." (PMID 37596667, 2023).
colorectal cancer (continued). "For example, LINC00920 blocked the ubiquitination of IGF2BP2 and maintained the MYC‐mediated glycolysis process in colorectal cancer." (PMID 35789547, 2023). "CCAT1-L is not the only lncRNA involved in MYC enhancer–promoter interactions: the MYMLR lncRNA transcribed antisense to MYC also facilitates these contacts to upregulate the proto-oncogene in colorectal cancer." (PMID 37444543, 2023). "In colon cancer where MYC is a potent oncogenic driver, inhibition of eIF4A by silvestrol reduces MYC translation and inhibits tumor growth in a mouse model of colorectal cancer." (PMID 36969025, 2023). "BI8622 and BI8626, identified through high-throughput screening, were found to inhibit the enzyme activity of HUWE1, repress MYC-dependent transactivation, and restrict the growth of colorectal cancer cells." (PMID 36831013, 2023). "ZKN-157 thus represents a new class of ribosome modulators that display cancer selectivity through specific ribosome inhibition in the CMS2 subtype of colorectal cancer potentially targeting MYC-driven addiction to high protein translation." (PMID 37377612, 2023). "miR-96 indirectly mediated AMPKα2 to achieve MYC upregulation to enhance the aggressive ability of colorectal cancer, which can be a promising novel target to prolong survival time of patients." (PMID 36875073, 2023). "As far back as 1996, the overexpression of c-MYC is considered as a good prognostic factor for survival in colorectal cancer." (PMID 37404762, 2023). "Cell culture experiments suggest that CCAT1 and MYC propagate a more invasive phenotype in metastatic colorectal cancer cells." (PMID 37347737, 2023). "For colorectal cancer, ribosomal biogenesis has been regarded as the integrator or final effector of the major altered signaling pathways in tumorigenesis, such as MYC and KRAS." (PMID 37373047, 2023). "Via in vitro experiments, CCNA2, CCNB1, and MYC expression was verified in 25 colorectal cancer tissue pairs." (PMID 37504265, 2023). "TTT has an important role in sustaining the activities of these oncogenic transcription factors, including c-MYC and E2Fs, in colorectal cancer cells." (PMID 37298208, 2023). "Collectively, we found that the c-MYC S405 phosphorylation stabilized the c-MYC protein and promoted colorectal cancer cell proliferation in vitro." (PMID 37596667, 2023). "This work has translational implications for CMS2 colorectal cancers and potentially other cancer subtypes that harbor high MYC activation and thus potential addiction to high protein translation capacity." (PMID 37377612, 2023). "We corroborated that NEK8-mediated colorectal cancer cell proliferation depends on the phosphorylation of c-MYC at the serine 405 sites." (PMID 37596667, 2023). "A study reveals that CAF-derived exosomal miR-17-5p promotes an aggressive phenotype in colorectal cancer by initiating a RUNX3/MYC/TGF-β1 positive feedback loop." (PMID 37719863, 2023). "To further clarify the correlation between NEK8 signaling and MYC signaling in colorectal cancer progress, we constructed SW48 and Lovo cells stably expressing Vector + shNC, NEK8 + shNC, NEK8 + shc-MYC#1, NEK8 + shc-MYC#2." (PMID 37596667, 2023). "In a longer period of time, although there is a certain risk of increased MYC gene expression, we also believe that BD5115 metabolites have an inhibitory effect on colorectal cancer." (PMID 35369066, 2022). "For instance, a mechanism involving Wnt/β-catenin, Hedgehog, MAPK signaling or TGF-β pathway compensates for the effects of BRD4 inhibition on MYC expression or protein stability in leukemia, hepatocellular carcinoma, and pancreatic and colorectal cancer." (PMID 35408939, 2022).
colorectal cancer (continued). "For instance, the lncRNA LINRIS blocks the ubiquitination of K139 in IGF2BP2 and prevents its degradation through the autophagy-lysosomal pathway, thus maintaining MYC-mediated glycolysis and promoting the proliferation of colorectal cancer cells." (PMID 35299748, 2022). "Another study showed that cAMP inhibits MYC activity through the mTOR pathway in a PDE4-dependent manner in colorectal cancer cells." (PMID 35978822, 2022). "Only 2 colorectal cancer cell lines with BRAF mutations RKO and HT-29 show MYC amplifications and both are more sensitive to the NUAK inhibitor WZ4003 than the mean sensitivity of the BRAF mutant group of colorectal cancer cell lines." (PMID 36295658, 2022). "c-MYC is one of the most important factors involved in colorectal cancer (CRC) initiation and progression; indeed, it is found to be upregulated in up to 80% of sporadic cases." (PMID 36230763, 2022). "FTO is upregulated in colorectal cancer and interacts with MYC to accelerate cell proliferation and migration." (PMID 35186927, 2022). "MYC upregulation is a valuable biomarker for neoadjuvant chemotherapy in primary colorectal cancer with liver metastasis." (PMID 36119478, 2022). "Though it is well documented in the literature that MYC is a driver of colorectal cancer, its potential role in EOCRCs is less clear." (PMID 36139061, 2022). "The knockdown of lncRNA LINRIS was reported to attenuate MYC-mediated aerobic glycolysis downstream of IGF2BP2 in colorectal cancer cells." (PMID 35002506, 2022). "In this study, gene expression analyses indicated that the expression of some PVT1 spliced linear transcripts, CircPVT1, CASC11, and MYC is increased in colorectal cancer (CRC)." (PMID 36052265, 2022). "Previous work established that small-molecule inhibitor of HUWE1 E3 ligase stabilizes MIZ1 and inhibits MYC-dependent transactivation in colorectal cancer cells." (PMID 36384931, 2022). "Combined treatment with BET and MEK inhibitors was reported to promote anaplastic thyroid tumors and colorectal cancer regression via synergistic suppression of MYC transcription." (PMID 35468095, 2022). "Studies have shown that the copy number of the NSUN2 gene is significantly increased in colorectal cancer, and the RNA methyltransferase NSUN2 is associated with the oncogene MYC." (PMID 35614935, 2022). "Subsequently, we investigated the potential for MYC S146L to enhance cancer hallmarks in an established colorectal cancer cell line, HCT116." (PMID 36018850, 2022). "We also analyzed components of the affected pathways, including RAS, WNT, NOTCH, Hippo, MYC, TGF-beta, and other pathways associated with the development of colorectal cancer, and compared them between the low and high MTOR expression groups." (PMID 35883111, 2022). "MZF1 reportedly interacts with c-MYC to promote cancer progression in colorectal carcinoma, lung adenocarcinoma, and glioma." (PMID 36499054, 2022). "Conversely, when a low level of AMPKα2 leads to an increase in the expression of FTO, the expression of MYC increases, which promotes the proliferation of colorectal cancer cells." (PMID 33926508, 2021). "CD133 and AXL have been described as cancer stem cell markers, and c-MYC as a key regulatory cellular mechanism in colorectal cancer (CRC)." (PMID 34669880, 2021). "In KRAS mutation-driven colorectal cancer, Rad51 has been reported to be transcribed by the KRAS downstream target MYC and to participate in the irradiation-induced DNA damage response and repair." (PMID 34215272, 2021). "Increased glutamine metabolism resulting from CDK4/6 inhibition in breast and colorectal cancer cells has been shown to be dependent on MYC-driven activation of mTOR." (PMID 33572972, 2021). "SMS, a polyamine biosynthetic enzyme, is overexpressed in patients with colorectal cancer and collaborates with MYC to promote colorectal cancer cell survival." (PMID 33869278, 2021).
colorectal cancer (continued). "In colorectal cancer, risk SNP rs6983267 was found to increase TCF7L2 binding and enhancer activity to regulate c-MYC expression." (PMID 33095866, 2021). "A recent high-throughput screening (HTS) has identified small molecule inhibitors of HUWE1, BI8622 and BI8626, that suppress transactivation of MYC target genes while increasing transrepression and the induction of apoptosis in colorectal cancer cells." (PMID 34178666, 2021). "Sonia 29 reported that hypusinated EIF5A directly regulate MYC biosynthesis and promotes growth of colorectal cancer cells." (PMID 34234848, 2021). "In colorectal cancer, studies found that c-MYC had the greatest stimulatory effect on promoters containing the A allele, and interestingly MAD1 was only effective at repressing ODC1 promoter activity in promoters containing the A allele." (PMID 33918978, 2021). "According to COSMIC, EGFR and MYC, the copy number gain rate in large intestine cancer is 3.48% and 7.8%, respectively, which is higher than the frequency of CNVs identified in the validation set of this study." (PMID 34680263, 2021). "MYC has an important role in cell proliferation, differentiation, survival, apoptosis, cancer stemness, as well as in drug resistance in colorectal cancer stem cells." (PMID 34771571, 2021). "A common lncRNA-induced disarragement of glucose metabolism in colorectal cancer (CRC) is mediated via the c-MYC oncogene." (PMID 33652661, 2021). "MYC has an important role in cell proliferation, differentiation, survival, apoptosis, cancer stemness, and in drug resistance in colorectal cancer stem cells." (PMID 34771571, 2021). "Inhibition of BRD4 by thienotriazolodiazepine JQ1 in colorectal cancer cells reduces MYC expression and inhibits cell proliferation." (PMID 34440124, 2021). "New studies have suggested that in colorectal cancer, L-tryptophan is preferentially converted to L-kynurenine due to the upregulation of the MYC oncogene." (PMID 34064065, 2021). "For example, CCAT1, which is transcribed from super-enhancer upstream of MYC, promotes transcriptional activation of MYC by promoting chromatin looping that places CCAT1 in the proximity to MYC with the recruitment of CTCF in human colorectal cancer." (PMID 33808647, 2021). "Mechanistically, increased glutamine metabolism resulting from CDK4/6 inhibition in breast and colorectal cancer cells has been shown to be dependent on MYC-driven activation of mTOR." (PMID 33572972, 2021). "SE-lncRNA CCAT1-L interacts with CTCF and mediate long-range promoter–enhancer interactions at MYC loop regions to regulate MYC expression in colorectal cancer." (PMID 34589487, 2021). "The amplification-based MYC oncogene has been found in various solid tumors, including kidney and colorectal cancers and BC subtypes, including TNBC, indicating MYC amplification as a frequent driver mutation in cancer." (PMID 32235890, 2020). "Of note, all the cell lines used in these studies were all MYC amplified, and in the case of the colorectal cancer cell lines, also PVT1 amplified." (PMID 32083000, 2020). "To evaluate the effect of miR-31-3p, miR-143 and miR-145 on the c-MYC expression in colorectal cancer, we deregulated these miRs in two anti-EGFR resistant cell lines: KRAS mutated (p.G13D) HCT116 and KRAS mutated (p.G12V) SW480 cell line." (PMID 32164324, 2020). "Nevertheless, MYC-repressed lncRNA LPP-AS2 was found to be downregulated in colorectal cancer and inhibited cell proliferation by regulating GADD45A." (PMID 32962742, 2020). "The first evidence of PVT1 in human solid malignancies, and also its relationship with MYC, came from the study of COLO320, a colorectal cancer cell line that was known to be MYC amplified." (PMID 32083000, 2020). "The expression of the protooncogene MYC is significantly upregulated in up to 70% of colorectal cancer (CRC) patients." (PMID 33299870, 2020).
colorectal cancer (continued). "Another recent study also suggested a role for H3K79 methylation at the MYC promoter/gene in colorectal cancer cells." (PMID 32814769, 2020). "Here, the authors show that a polyamine biosynthetic enzyme, spermine synthase, is overexpressed in colorectal cancers and cooperates with MYC to prevent cancer cell apoptosis by repression of proapoptotic protein, Bim." (PMID 32591507, 2020). "We show here that hypusinated EIF5A promotes growth of colorectal cancer (CRC) cells by directly regulating MYC biosynthesis at specific pausing motifs." (PMID 33303756, 2020). "Even though BKZ-3 was less sensitive for MYC/NMYC inhibition in comparison to BKZ-2, both colorectal cancer cell lines revealed significant reductions of survival rates due to induced apoptosis upon MYC/NMYC inhibition." (PMID 32927768, 2020). "In colorectal cancer stem cells (CCSC) the myc proto-oncogene protein (MYC) was reported to be consistently overexpressed, contributing to self-renewal and pluripotency as well as drug resistance." (PMID 32927768, 2020). "For example, CCAT1‐L and CCAT2 form attractive targets to specifically inhibit MYC transcription in colorectal cancer." (PMID 30451365, 2019). "Of interest, a recent report showed that glutamine starvation can inhibit MYC protein accumulation and MYC-dependent gene transcription in colorectal cancer." (PMID 31212591, 2019). "For example, high copy numbers of ERBB2, TOP2A, CCND1, EGFR and MYC are observed in many colorectal cancers." (PMID 31009485, 2019). "Genes known to be dysregulated in colorectal cancers, such as MYC and CCND1, were also found to be highly and significantly up-regulated in our RNA-seq analysis, which was further validated by RT-qPCR analysis." (PMID 32082365, 2019). "Two MYC regulated lncRNAs, MYCLo-1 and MYCLo-2, have also been shown to repress genes that promote colorectal cancer cell proliferation in a MYC-dependent manner." (PMID 31881017, 2019). "MYC transcription was also found to be increased in tumor specimens from the 4 cohorts of colorectal cancer patients." (PMID 30575780, 2018). "AP4 is expressed in progenitor/transient-amplifying (TA) cells in human colonic crypts, and in colorectal cancer (CRC) in a pattern similar to c-MYC." (PMID 30177706, 2018). "Another is Ddx21 [DEAD (Asp-Glu-Ala-Asp) box helicase 21], which has been demonstrated to be a coexpression marker with c-MYC in colorectal cancer and is known to be directly transcribed by c-Myc." (PMID 32161797, 2018). "A high c-MYC and SIRT1 protein co-expression has been demonstrated to be associated with malignant transformation of specific colorectal cancer subtypes." (PMID 29383100, 2017). "Amongst these was Pvt1, a lncRNA previously reported to be a marker of poor prognosis in colorectal cancer and shown to be required in MYC-driven cancers." (PMID 28875933, 2017). "Capture Hi-C tech has also been applied to the study of colorectal cancer and used to identify long-range interactions between rs6983267 (later shown to contain multiple enhancers) and a MYC promoter mediated by the MYC-related lncRNA CCAT1." (PMID 29149895, 2017). "The MYC oncogene has long been established as a central driver of many types of human cancers, including colorectal cancer." (PMID 28036279, 2017). "We report that the DNA double‐strand break repair (DSB repair) by homologous recombination (HR) pathway was enhanced in KRAS‐mutant colorectal cancer cells through hyperactivation of c‐MYC." (PMID 28173629, 2017). "In colorectal cancers it has been shown that β-catenin/TCF4 complexes compete with TCF3 to bind to the MYC promoter, and β-catenin/TCF4 induces its expression while TCF3 represses it." (PMID 27228072, 2016). "For example, the alkylating agent Temozolamide (used to treat glioblastoma multiforme) shows activity in MYC amplified colorectal cancer lines (present in 33% of primary tumors)." (PMID 27397505, 2016).